PRDX6 (peroxiredoxin 6)
Diseases named in the same sentence as PRDX6 in open-access papers (continued):
Sharing a sentence is not in itself a finding about the gene and the disease.
ovarian carcinoma (continued). "Moreover, the ectopic expression of PRDX6 markedly elevated NNMT protein level in ovarian cancer cells." (PMID 39887931, 2025). "Immunoblotting analysis showed that overexpression of PRDX6 obviously promoted the activation of MAPK signaling pathway in ovarian cancer cells, as evidenced by increased phosphorylation levels of extracellular signal‐regulated kinase (ERK), c‐Jun N‐terminal kinase (JNK), and p38." (PMID 39887931, 2025). "Notably, ovarian cancer patients exhibiting high protein levels of both PRDX6 and NNMT showed worse overall and progression‐free survival." (PMID 39887931, 2025). "Compared with parental cells, KO of PRDX6 significantly reduced the half‐life of NNMT protein, whereas ectopic expression of PRDX6 markedly prolonged the half‐life of NNMT protein in ovarian cancer cells, suggesting that PRDX6 enhances the protein stability of NNMT." (PMID 39887931, 2025). "Notably, the frequency of increased mRNA level of PRDX6 in ovarian cancer tissues ranked top among all PRDX members by analyzing the cBioportal database." (PMID 39887931, 2025). "In addition, treatment with the proteasome inhibitor MG132 obviously increased NNMT protein level, and rescued PRDX6 KO‐mediated decrease of NNMT protein level in ovarian cancer cells." (PMID 39887931, 2025). "In addition, withangulatin A, a covalent PRDX6 inhibitor which inhibited the peroxidase and PLA2 activities of PRDX6, profoundly suppressed the growth, migration, and invasion of ovarian cancer cells." (PMID 39887931, 2025). "In addition, the expression of PRDX6 was positively correlated with its copy number in ovarian cancer tissues." (PMID 39887931, 2025). "In this study, we show a nonenzymatic mechanism underlying PRDX6's tumor‐promoting role in ovarian cancer." (PMID 39887931, 2025). "Down-regulation of Prdx6 with specific siRNA decreased proliferation and induced apoptosis in canine haemangiosarcoma cells, whereas overexpression of Prdx6 attenuated apoptosis in ovarian cancer cells and promoted growth of lung tumors in mice through activation of JAK2/STAT3 signaling." (PMID 31652719, 2019). "Furthermore, high PRDX6 mRNA expression was found to be correlated with poorer OS in grade III ovarian cancer patients." (PMID 30104402, 2018). "Furthermore, overexpression of PRDX6 attenuated cisplatin-induced apoptosis by reducing ROS levels in SKOV-3 ovarian cancer cells and led to the development of cisplatin resistance." (PMID 30104402, 2018). "Nevertheless, publications about PRDX6 in ovarian cancer are limited." (PMID 30104402, 2018). "Furthermore, overexpression of PRDX6 was correlated with poorer OS in all ovarian cancer patients treated with Taxol and Taxol+Platin chemotherapy, while PRDX6 indicated a poor PFS in all ovarian cancer patients treated with Platin chemotherapy." (PMID 30104402, 2018). "Therefore, our current results demonstrate that PRDX6 overexpression is a significant indicator of poor clinical outcome for ovarian cancer patients." (PMID 30104402, 2018). "PRDX6 overexpression attenuated cisplatin-induced apoptosis in human ovarian cancer cells." (PMID 28432271, 2017). "PRDX6 overexpression attenuates cisplatin-induced apoptosis in human ovarian cancer cells; SKOV-3." (PMID 26061816, 2015). "Similarly, NNMT KD could also compromise the tumor‐promoting effect of PRDX6‐MUT in ovarian cancer cells." (PMID 39887931, 2025). "Interestingly, reconstituted expression of the enzymatically dead mutant PRDX6‐MUT could still partially, but markedly, rescue PRDX6 KO‐induced growth inhibition of ovarian cancer cells." (PMID 39887931, 2025). "PRDX6‐mediated NNMT upregulation thus promotes the growth and metastasis of ovarian cancer cells by activating the mitogen‐activated protein kinase (MAPK) pathway." (PMID 39887931, 2025).
ovarian carcinoma (continued). "Here, it is shown that the 1‐cysteine PRDX (PRDX6) upregulates nicotinamide N‐methyltransferase (NNMT) to promote the growth and metastasis of ovarian cancer cells, independently of PRDX6's enzymatic activities." (PMID 39887931, 2025). "Collectively, these data demonstrate that PRDX6 stabilizes and upregulates NNMT protein levels by inhibiting its ubiquitin‐mediated degradation in ovarian cancer cells." (PMID 39887931, 2025). "Collectively, these results indicate that PRDX6‐mediated NNMT upregulation promotes the growth and metastasis of ovarian cancer cells by activating MAPK signaling." (PMID 39887931, 2025). "Overall, these results indicate that PRDX6 prevents NNMT ubiquitination at lysine 23 and 210, leading to the inhibition of proteasomal degradation and upregulation of NNMT in ovarian cancer cells." (PMID 39887931, 2025). "Our study found that PRDX6‐mediated NNMT upregulation activates MAPK pathway, thereby provoking the proliferation and metastasis of ovarian cancer cells." (PMID 39887931, 2025). "Our study showed that PRDX6 interacts with NNMT to diminish its proteasomal degradation, leading to the upregulation of NNMT in ovarian cancer." (PMID 39887931, 2025). "Together, these data suggest that PRDX6 competitively interacts with NNMT to prevent TRIM56‐mediated NNMT ubiquitination, leading to NNMT upregulation in ovarian cancer cells." (PMID 39887931, 2025). "Taken together, these observations indicated that PRDX3, PRDX5, and PRDX6 overexpression could lead to the chemotherapy resistance in ovarian cancer and therapeutic strategies targeting these isoforms may therefore be an effective anticancer therapy for ovarian cancer." (PMID 30104402, 2018). "Meanwhile, PRDX6 predicted poor PFS for all ovarian cancer patients, endometrioid ovarian cancer patients, stages I and II ovarian cancer patients." (PMID 30104402, 2018). "We generated PRDX6 knockout (KO) ovarian cancer cells using CRISPR/Cas9 genome editing and then performed cell viability and colony formation assays to examine the effect of PRDX6 on the growth of ovarian cancer cells." (PMID 39887931, 2025). "In addition, PRDX6‐mediated NNMT upregulation activates mitogen‐activated protein kinase (MAPK) signaling, thereby promoting the growth and metastasis of ovarian cancer cells." (PMID 39887931, 2025). "In detail, PRDX6 competitively interacts with NNMT to prevent its binding to the E3 ubiquitin ligase TRIM56, resulting in the inhibition of ubiquitin‐mediated degradation of NNMT to activate MAPK signaling pathway and promote ovarian cancer progression." (PMID 39887931, 2025). "PRDX6 KO profoundly diminished the migration and invasion of SKOV3 and A2780 cells, whereas overexpression of PRDX6 obviously increased the migration and invasion of ovarian cancer cells." (PMID 39887931, 2025). "The nonenzymatic mechanism of PRDX6 in promoting ovarian cancer progression underscores the upregulation of NNMT." (PMID 39887931, 2025). "To investigate the effect of the PRDX6‐NNMT axis on the growth of ovarian cancer cells in vivo, we generated a mouse xenograft model by subcutaneously inoculating PRDX6‐overexpressing SKOV3 cells with or without NNMT KD into immunodeficient mice." (PMID 39887931, 2025). "PRDX6 interacts with and upregulates NNMT via preventing TRIM56‐mediated ubiquitination and proteasomal degradation, thereby activating MAPK signaling and promoting ovarian cancer progression." (PMID 39887931, 2025). "In this study, we reveal a nonenzymatic mechanism of PRDX6 in promoting ovarian cancer progression." (PMID 39887931, 2025). "Interestingly, by knocking down NNMT in PRDX6‐WT‐overexpressing cells, we found that NNMT KD markedly abolished the promoting effect of PRDX6‐WT on the growth and proliferation of ovarian cancer cells, as evidenced by cell viability and colony formation assays." (PMID 39887931, 2025).
ovarian carcinoma (continued). "Given that PRDX6 upregulates NNMT independently of its enzymatic activities, we next investigated whether NNMT upregulation contributes to PRDX6's nonenzymatic function in promoting ovarian cancer progression." (PMID 39887931, 2025). "In conclusion, our results demonstrated that beyond its canonical enzyme activities, PRDX6 promotes the malignant progression of ovarian cancer through a nonenzymatic mechanism, by which PRDX6 interacts with NNMT and suppresses TRIM56‐mediated ubiquitination degradation of NNMT." (PMID 39887931, 2025). "Last but not least, there is no available research about the exact function of PRDX5 and PRDX6 in BrCa, but overexpression of PRDX5 and prognostic values have been observed in numerous cancers, including ovarian cancer and endometrial cancer." (PMID 31402980, 2019).
hepatocellular carcinoma (13 papers, 2016 to 2025). A malignant tumor that arises from hepatocytes. "This research aimed to study the expression of PRDX6 mRNA in hepatocellular carcinoma (HCC) and its effect on the prognosis of HCC." (PMID 38544826, 2024). "In this work, we demonstrated that knocking out PRDX6 in SNU475 hepatocellular carcinoma cells prevents cell proliferation, migration, and invasiveness." (PMID 37371884, 2023). "Although PRDX6-aiPLA2 activity has been shown to promote cancer cell death induced by TNFα in hepatocellular carcinoma, previous research using specific pharmacologic inhibitors and mutagenesis studies has demonstrated the critical roles played by both enzyme activities for lung tumor development." (PMID 40298631, 2025). "Specifically, the expression of PRDX6 is documented to elevate in the sera of patients with lung squamous cell carcinoma or hepatocellular carcinoma, but decrease in both the sera of patients with esophageal or colon carcinoma and the interstitial fluid of patients with breast cancer." (PMID 40298631, 2025). "Currently, the role of PRDX6 in hepatocellular carcinoma remains elusive." (PMID 38544826, 2024). "Therefore, in this study, the expression, prognostic impact and clinical significance of PRDX6 mRNA in hepatocellular carcinoma (HCC) were analyzed using the TCGA database." (PMID 38544826, 2024). "Targeting PRDX6 activity or expression may emerge as a novel therapeutic strategy against hepatocellular carcinoma disease progression." (PMID 37371884, 2023). "We investigated whether Lp(a) alone could promote changes in the antioxidant enzymes, GPx1, Prdx6, and Sod1, by incubating purified Lp(a) with human hepatoma cells." (PMID 30596094, 2018). "Therefore, the mechanism behind the effects of loss of PRDX6 in HCT116 cells could differ from that in HepG2 cells which is coherent with the fact that the correlation of PRDX6 expression with patient survival is different in hepatocellular carcinomas." (PMID 39061949, 2024). "Therefore, deletion of PRDX6 could potentially be incorporated as part of a combination therapy approach against hepatocellular carcinoma to impede tumor progression and metastasis." (PMID 37371884, 2023). "HPA analysis of protein expression showed that PRDX6, GCLM, HTATIP2, NOL10, KIF18A, RAP2A and GDI2 were highly expressed in the hepatocellular carcinoma tissues compared with normal control tissues." (PMID 34760691, 2021). "However, in hepatocellular carcinoma, PRDX6 was lower expressed in the tumor than the non-tumor tissues and its decrease was associated with poor prognosis 25, indicating its anti-tumor function in liver cancer." (PMID 32231717, 2020). "Our prior studies have shown that a lack of PRDX6 diminishes NRF2 levels in the SNU475 cell line and alters redox proteome in the HepG2 hepatocellular carcinoma cell line leading to decreased cell proliferation by repression of cell cycle progression." (PMID 39061949, 2024).
colorectal cancer (10 papers, 2015 to 2024). A primary or metastatic malignant neoplasm that affects the colon or rectum. "This correlation differs for liver and colorectal tumors, making it relevant and novel to study for the first time the effect of PRDX6 deficiency in the colorectal cancer line HCT116." (PMID 39061949, 2024). "The expression of PRDX6 can promote the proliferation, migration, and invasion of colorectal cancer cells." (PMID 36741702, 2022). "Among them, previous reports have demonstrated that PRDX6 is overexpressed in a variety of cancers and is involved in the tumor progression of different tumors, such as those in lung 25, thyroid 26 and colorectal cancer." (PMID 32201510, 2020). "Peroxiredoxin-6 (PRDX6), an upregulated protein after baicalein treatment, was found to decrease the generation of ROS and inhibit the growth of colorectal cancer cells." (PMID 26568766, 2015). "Here, using CRISPR/Cas9 technology, we constructed an HCT116 colorectal cancer cell line knockout for PRDX6 to study whether the mechanisms described for other cancer cells in terms of proliferation, migration, and invasiveness also apply in this tumoral cell line." (PMID 39061949, 2024). "The effect of PRDX6 loss has been studied in two tumoral hepatocarcinoma cell lines with different degrees of differentiation, HepG2 and SNU475, but, still, it is unknown whether it can be extrapolated to other tumors including human colorectal carcinoma." (PMID 39061949, 2024). "The up-regulation of both PRDX2 and PRDX6 is described in many tumors and correlated with invasiveness, migration, drug resistance and enhancing stem cell properties, in particular in NSCLC, colorectal cancer, and esophageal carcinoma." (PMID 34320944, 2021). "All these findings suggest a role of PRDX6 in HCT116 dedifferentiation characterized by high levels of N-cadherin and increased levels and activity of metalloproteinases which could contribute to the metastatic features of colorectal cancer cells." (PMID 39061949, 2024).
melanoma (10 papers, 2007 to 2025). A malignant, usually aggressive tumor composed of atypical, neoplastic melanocytes. "PRDX6 is upregulated in human melanoma cells, increases cell proliferation by activating Src signaling via the production of arachidonic acid, and its expression depends on EGFR signaling." (PMID 34067095, 2021). "PRDX6 can also be involved in tumor progression, since it was shown that its expression correlated with melanoma malignancy." (PMID 34943045, 2021). "It was reported that PRDX6 expression in melanoma cells is maintained in a post-transcriptional manner by EGFR-dependent signaling, implying a link between PRDX6 and EGFR signaling." (PMID 37529008, 2023). "Although PRDX6, MAGOHB, NUCKS1, DCAF13, and TXN genes as a panel displayed weak prediction of ICB response, the panel robustly stratified overall survival in patients with melanoma treated with anti-PD1 following progression on anti-CTLA4 therapy." (PMID 37835514, 2023). "de Souza and colleagues observed decreases in the expression of PRDX2 and PRDX6 proteins in murine melanoma line Tm1 compared with Tm5 from nontumor cells." (PMID 17980029, 2007). "In Xiphophorus malignant melanoma tissue, oxidative stress increases and is correlated with upregulation of the antioxidative proteins, glutathione-S-transferase mu3 (GST mu3) and peroxiredoxin-6 (PRDX6), but not PRDX2, which was subject to a non-significant increase." (PMID 34067095, 2021).
infertile (9 papers, 2014 to 2024). "Prdx6−/− mice have high levels of tyrosine nitration in their spermatozoa, which are associated with infertility." (PMID 35204109, 2022). "Altogether, these findings strongly suggest an essential role of PRDX6 in the protection of human spermatozoa against oxidative stress and offer a possible cause for the impaired sperm function in idiopathic infertile patients." (PMID 32668798, 2020). "Indeed, infertile men with a deficiency in PRDX6 peroxidase activity (or the PRDX6 protein) in their spermatozoa are at higher risk from the damage caused by ONOO−-induced lipid peroxidation, even if they take α-tocopherol supplements." (PMID 32668798, 2020). "Thus, the absence or inactivation of PRDX6 is a plausible cause of sperm DNA damage in infertile men." (PMID 32668798, 2020). "In contrast, deficiency of PRDX6 results in spermatozoal oxidative stress/damage and injures male fertility, while decreased spermatozoal PRDX6 levels were also found in infertile patients." (PMID 38790639, 2024). "Since γ-tocopherol is an efficient ONOO− scavenger (better than α-tocopherol), these results suggest that ONOO− is the primary culprit for the infertility phenotype observed in Prdx6−/− males." (PMID 35204109, 2022). "Previously, we reported that PRDX6 is present in low amounts in spermatozoa from idiopathic infertile men." (PMID 32668798, 2020). "Low levels of PRDX6 were observed in infertile men, positioning PRDX6 as the first line of defense against oxidative stress in human spermatozoa." (PMID 31905831, 2019). "In terms of PRDXs expression in spermatozoa, the population of infertile men is heterogeneous; sperm PRDX6 was low in 67% and 39% varicocele and idiopathic infertile patients, respectively, whereas sperm PRDX1 was only low in 42% of varicocele patients." (PMID 25780579, 2014). "We observed that in infertile men with varicocele or idiopathic infertility with high levels of lipid peroxidation in the seminal plasma and spermatozoa, the amount of DNA damage depends on the level of thiol-oxidized PRDX6 in their spermatozoa." (PMID 32668798, 2020). "Thus, it is possible that failure to achieve fatherhood resides in the inactivation of PRDX6 iPLA2 in spermatozoa of infertile men." (PMID 30477206, 2018). "Furthermore, these results support our previous findings indicating that infertile men with low amounts of PRDX6 or having high levels of thiol oxidation of PRDX6 in their spermatozoa displayed reduced motility." (PMID 29021631, 2017). "Interestingly, sperm levels of high molecular mass complexes of hyperoxidized PRDX6 were higher in both infertile men groups than in donors and the PRDX6 thiol oxidation ratio correlated with levels of lipid peroxidation in spermatozoa." (PMID 25780579, 2014). "Indeed, we observed that spermatozoa from infertile patients with either clinical varicocele or idiopathic infertility had lower levels of PRDX6, which correlated with low motility and high levels of lipid peroxidation and DNA damage compared to fertile controls." (PMID 30477206, 2018). "Although seminal plasma and all subcellular sperm compartments contain PRDXs, ensuring an effective first-line defense against ROS, spermatozoa from infertile men display lower amounts of PRDX1 and PRDX6 with a relatively high degree of thiol oxidation." (PMID 33924936, 2021). "Although PRDXs are largely distributed in seminal plasma as well as in all subcellular sperm compartments, spermatozoa from infertile men exhibit lower amounts of PRDX1 and PRDX6 with a relatively high degree of thiol oxidation which inhibits PRDX activities." (PMID 33924936, 2021). "Collectively, these results suggest that the absence of PRDX6 peroxidase is sufficient to promote the ONOO−-induced protein tyrosine nitration that leads to infertility, as observed in the C47S and Prdx6−/− males." (PMID 35204109, 2022).
infertile (continued). "The total quantity of PRDX1 and PRDX6, but not for PRDX4 and PRDX5, is lower in spermatozoa from varicocele patients (prior to surgery) than in idiopathic infertile men or healthy donors." (PMID 25780579, 2014). "PRDX6, but not PRDX1, is present in low amounts in seminal plasma of infertile men with clinical varicocele." (PMID 25780579, 2014).